SYN1 (synapsin I)
Diseases named in the same sentence as SYN1 in open-access papers (continued):
Sharing a sentence is not in itself a finding about the gene and the disease.
breast carcinoma (3 papers, 2013 to 2024). "In light of all the evidence relating extracellular matrix alterations and cancer development, the present work aimed to elucidate the possible role of HPSE1, heparan sulfate (HS) and Syn-1 in breast cancer cell resistance to trastuzumab." (PMID 24083474, 2013). "A heterotypic cell fusion assay was set up with the three M13SV1 cell lines (wild type, ASCT2KO, Syn1 overexpression), which were freshly transfected with an miCP vector coding for the iCre recombinase and the three breast cancer cell lines MDA-MB-231_pFDR.2, MDA-MB-435S_pFDR.1 and HS578_pFDR." (PMID 38891857, 2024). "The increased levels of Syn-1 observed in breast cancer lymphocytes, after lymphocyte exposure to the plasma of breast cancer patients and after co-culture with MCF-7 cells suggested that Syn-1 shedding could induce heparanase expression." (PMID 30922347, 2019). "Breast cancer cell lines responsive to trastuzumab present higher amounts of HER2, Syn-1 and HS on the cell surface, but lower levels of secreted HS." (PMID 24083474, 2013).
COVID-19 (3 papers, 2021 to 2023). A disease caused by infection with severe acute respiratory syndrome coronavirus 2. "Previous data suggest that high SYN-1 levels are a potential marker for COVID-19 progression or severity, as they are associated with more severe endothelial damage and inflammatory reactions." (PMID 37585916, 2023). "Accordingly, increased levels of HS (the main substrate of HPSE), HA and Syn-1 demonstrated eGC shedding in COVID-19." (PMID 35757776, 2022). "The comparison between COVID-19 patients showed that children with mild symptoms had higher mRNA concentrations of HERV genes than those with severe complications (significantly for all, but SYN1 and SYN2) or MIS-C (significantly for all, but borderline values for SYN1)." (PMID 34299101, 2021).
Seizure (3 papers, 2018 to 2022). A seizure is an intermittent abnormality of nervous system physiology characterized by a transient occurrence of signs and/or symptoms due to abnormal excessive or synchronous neuronal activity in the brain. "Epileptic seizures were reported in 82% (64/78) of the total number of individuals with putatively disease-causing SYN1 variants." (PMID 36568968, 2022). "Mutation (Q555X) of the X-linked SYN1 gene that encodes a neuronal phosphoprotein synapsin I has been reported in patients with inherited reflex seizures that can be triggered by bathing, nail clipping, and face-rubbing, with potential epileptogenic network involving the temporo-insular region." (PMID 34616357, 2021). "Our results suggest that epileptic seizures observed in MRD7 patients could be induced by defects in SYN1 regulation." (PMID 30115750, 2018).
septic shock (3 papers, 2021 to 2023). Shock caused by infection; frequently caused by gram negative bacteria, although some cases have been caused by other bacteria, viruses, fungi, and protozoa; characterized by fever, chills, tachycardia, tachypnea, and hypotension. "Concentrations of SYN-1, S1P, soluble VE-cadherin and other biomarkers were measured on days 1, 2 and 7 in 375 patients with septic shock surviving up to 7 days after randomization." (PMID 33741039, 2021). "The purpose of this study is to investigate the time course of syndecan-1 (Syn-1) plasma levels, the correlation between Syn-1 and organ damage development, and the associations of Syn-1 level with cumulative fluid balance and ventilator-free days (VFD) in patients with septic shock." (PMID 33726863, 2021). "Plasma concentrations of SYN-1 were more than double in septic shock patients on day 1 (185 ng/mL) compared to healthy volunteers (p < 0.001), whereas the opposite was true for S1P (p < 0.001), with septic shock patients reporting values 3.5 times lower (86.5 [63.7–120.0] ng/mL)." (PMID 33741039, 2021). "Moreover, the highest Syn-1 level measured 1 to 3 days after ICU admission was defined as the Syn-1 level in the early stage of septic shock, and the highest Syn-1 level measured 5 to 7 days after admission was defined as the Syn-1 level in the late stage of septic shock." (PMID 33726863, 2021).
synucleinopathies (3 papers, 2022 to 2025). "For the first time a direct role of NFAT in aSyn-O-induced toxicity and Syn1 gene regulation was demonstrated, enlarging our understanding of the pathways underpinnings synucleinopathies." (PMID 37596531, 2023). "Together, these data demonstrate that A30P-aSyn-O can disrupt neuronal synapses by the activation of NFAT signaling pathway and subsequent downregulation of Syn1 expression suggesting NFAT pathway inhibition might be a target for pharmacological modulation in synucleinopathies." (PMID 37596531, 2023). "Accordingly, after the analysis of a panel of 91 genes related to various cellular processes involved in PD/synucleinopathies by real-time qPCR, and further validation at protein level, we found that aSyn-O modulate the gene involved in the maintenance of synapses, synapsin 1 (Syn1)." (PMID 37596531, 2023).
Cerebral ischemia (2 papers, 2020 to 2023). Restriction of arterial blood supply to the brain associated with insufficient oxygenation to support the metabolic requirements of the tissue. "The experimental results showed that, compared with MCAO model group, HGWD group could significantly enhance the synaptic density and expression of synaptic marker proteins (PSD95, Synapsin I), suggesting that HGWD could improve the synaptic plasticity damage caused by cerebral ischemia." (PMID 37650573, 2023).
endometrial carcinoma (2 papers, 2012 to 2019). A malignant tumor arising from the epithelium that lines the cavity of the uterine body. "Multiple types of cancer, including prostate adenocarcinoma and endometrial carcinoma, have elevated levels of Syn1 expression with further upregulation of Syn1 associated with cancer progression." (PMID 31776415, 2019). "Accordingly, CRH was found to induce cAMP in human endometrium via CRHR1 triggered protein-kinase A (PKA) and we recently found that Syn1 is induced via the cAMP pathway in endometrial carcinoma." (PMID 22971074, 2012).
fetal growth restriction (2 papers, 2021 to 2023). A fetus that does not grow beyond the 10th percentile of conventionally accepted weight for gestational age. "Makaroun and Himes reported lower placental methylation in the regulatory regions of the SYN1 gene along with an increase in its expression when comparing human fetuses presenting fetal growth restriction and small-for-gestational-age patients with a control group." (PMID 37108254, 2023). "It is certainly well-documented that altered regulation of syncytialization in the villous placenta may be integral to the increased STB turnover and release in conditions such as pre-eclampsia and fetal growth restriction and that syn1 may be involved in such dysfunction." (PMID 34638599, 2021).
meningioma (2 papers, 2018 to 2021). A generally slow growing tumor attached to the dura mater. "In the meningioma model (Syn5 and Syn1), all three drugs induced merlin-deficient-specific kinase networks that included MAPK proteins, PTK2 (FAK1) and ephrin receptor proteins among other kinases." (PMID 29897904, 2018).
reflex epilepsies (2 papers, 2022 to 2024). "Recent studies have highlighted a specific association of reflex epilepsy with SYN1 variants, but the percentage of patients exhibiting this phenotype and the full clinical spectrum associated with SYN1 remains undetermined." (PMID 36568968, 2022). "The SYN1 gene encodes synapsin I, variants within the SYN1 gene are linked to X-linked neurodevelopmental disorders with high clinical heterogeneity, with reflex epilepsies (REs) being a representative clinical manifestation." (PMID 38576531, 2024).
Shock (2 papers, 2021). The state in which profound and widespread reduction of effective tissue perfusion leads first to reversible, and then if prolonged, to irreversible cellular injury. "High levels of plasma Syn-1 in the early stage of septic shock are associated with positive cumulative fluid balance, and lower VFD and PaO2/FiO2." (PMID 33726863, 2021). "In the early stage of septic shock, the median Syn-1 level was 4 times higher in the high Syn-1 group than in the low Syn-1 group, and in the late stage of septic shock, it was 4.5 times higher in the high Syn-1 group than in the low Syn-1 group." (PMID 33726863, 2021). "In the largest study to date in patients with septic shock, alterations of the eGC and vascular permeability were assessed by assaying in plasma SYN-1, S1P and VE-cadherin, respectively." (PMID 33741039, 2021). "Because most of our patients with septic shock (97%) survived, we could not explore whether Syn-1 levels are correlated with 30-day mortality." (PMID 33726863, 2021). "The second important finding of the present study is that the relationship between high Syn-1 level over the 7 days after ICU admission and illness severity in early stage of septic shock were not identified except for pulmonary disturbances." (PMID 33726863, 2021).
tauopathy (2 papers, 2022 to 2023). Neurodegenerative disorders involving deposition of abnormal tau protein isoforms (tau proteins) in neurons and glial cells in the brain. "Furthermore, the expression of synapsin I C83 in the tau P301S transgenic mouse model of tauopathy and wild‐type mice shows similar pathological effects." (PMID 35443102, 2022). "The fE mice with or without Syn1-Cre were crossbred with mice expressing mutant 1N4R human microtubule-associated protein tau (MAPT) encoding the disease-associated P301S mutation (PS19 line), which has been widely utilized as a tauopathy mouse model." (PMID 37118426, 2023).
acute respiratory distress syndrome (1 paper, 2021). Progressive and life-threatening pulmonary distress in the absence of an underlying pulmonary condition, usually following major trauma or surgery. "Syn-1 plasma level, acute respiratory distress syndrome (ARDS), other organ damage, VFD, and cumulative fluid balance were assessed daily." (PMID 33726863, 2021).
B-cell lymphoma (1 paper, 2017). "The Syn1 depicted a nearly similar potential anticancer activity like BMAP-28 in B-cell lymphoma." (PMID 28322271, 2017).
bipolar disorder (1 paper, 2024). A disorder of the brain that causes unusual shifts in mood, energy, activity levels and the ability to carry out day-to-day tasks. "To investigate the function of bipolar disorder-related upregulated AP1AR-DT, we generated a recombinant AAV (rAAV) carrying AP1AR-DT (for AP1AR-DT overexpression, AP1AR-DTOE) driven under the human neuron specific synapsin I promoter and used an empty AAV vector as a control." (PMID 39558356, 2024).
celiac disease (1 paper, 2018). An autoimmune genetic disorder with an unknown pattern of inheritance that primarily affects the digestive tract. "Investigations of these manifestations in celiac disease have identified a number of associated immune abnormalities, including B cell reactivity towards various autoantigens, such as transglutaminase 3, transglutaminase 6, synapsin I, gangliosides, and collagen." (PMID 30127251, 2018). "The data from celiac disease patients demonstrate that only certain subsets of anti-gliadin antibodies cross-react with SYN1." (PMID 30127251, 2018).
coronary artery disease (1 paper, 2021). "SYN1 is an innovative myocardial perfusion imaging (MPI) agent and the most common imaging tool for noninvasive ischaemia evaluation in patients with suspected coronary artery disease (CAD)." (PMID 34830471, 2021).
dengue (1 paper, 2022). "According to the revised Starling model and based on data in diseases associated with leakage of intravascular fluid and proteins leading to oedema, such as dengue, we initially hypothesized that kwashiorkor would be associated with increased plasma levels of Syn1 and HA." (PMID 35398787, 2022).
Down syndrome (1 paper, 2022). "It is certainly possible, therefore, that overexpression of cell-associated or secretory SUPYN in TS21 could alter syn-1 activities in the brain and could therefore be associated with the neurodevelopmental and neurodegenerative aspects of Down syndrome." (PMID 35732788, 2022).
endometrial adenocarcinoma (1 paper, 2021). "We used HTR8 cells to model EVT because they were derived from primary EVT cells and are known to lack expression of syn1 and SUPYN and endometrial adenocarcinoma-derived Ishikawa cells to represent endometrial glandular epithelial cells." (PMID 34638599, 2021).
epileptic syndrome (1 paper, 2024). "A de novo variant, (GRCh37)ChrX:47483957_47483958insTC, was identified in the upstream region of SYN1 (synapsin 1) associated with an X-linked recessive neurodevelopmental/epileptic syndrome in males (OMIM:# 300491 and # 300115)." (PMID 38499569, 2024).
GM1 gangliosidosis (1 paper, 2020). A rare lysosomal storage disorder characterized biochemically by deficient beta-galactosidase activity and clinically by a wide range of variable neurovisceral, ophthalmological and dysmorphic features. "The GM1 gangliosidosis-derived mature neurons exhibited a similar number of SYNAPSIN I-positive puncta to control neurons." (PMID 32302553, 2020).
head and neck carcinoma (1 paper, 2018). A carcinoma that arises from the head and neck region. "In head and neck carcinomas, decreased or absent Syn1 expression is associated with aggressiveness and a poor prognosis." (PMID 29850393, 2018).
HPRT-deficiency (1 paper, 2013). "Our current data suggest a role for Synapsin I in the etiology of HPRT-deficiency; its reduced expression may contribute to the alteration of the dopaminergic neurotransmitter system in LND." (PMID 23691025, 2013).
Hypervolemia (1 paper, 2025). An increase in the amount of intravascular fluid, particularly in the volume of the circulating blood. "Despite an increase in NT-proBNP after fluid resuscitation (p < 0.001), Syn-1 levels appeared unaffected by this effect suggesting that inflammatory-driven glycocalyx degradation may be a more dominant factor than hypervolemia alone." (PMID 40685448, 2025). "Although hypervolemia has been known as a trigger for natriuretic peptide-induced glycocalyx shedding, the study did not describe any direct correlation between Syn-1 and N-terminal pro b-type natriuretic peptide (NT-proBNP) levels." (PMID 40685448, 2025).
injury (1 paper, 2024). Damage inflicted on the body as the direct or indirect result of an external force, with or without disruption of structural continuity. "Wuet al’s research concludes that supplementation of omega-3 fatty acids can restore cognitive function and normalize the action of BDNF, synapsin I, and CREB as well as oxidative damage after traumatic brain injury." (PMID 39810851, 2024).
leiomyoma (1 paper, 2018). A well-circumscribed benign smooth muscle neoplasm characterized by the presence of spindle cells with cigar-shaped nuclei, interlacing fascicles, and a whorled pattern.
malignant glioma (1 paper, 2021). A grade III or grade IV glioma arising from the central nervous system. "Consistent with the glial nature of malignant gliomas, genes downregulated at T2 and End were enriched for neuronal differentiation and synaptic functions (e.g., DCX, NEUROD2, and SYN1)." (PMID 33390587, 2021).
malnutrition (1 paper, 2022). Inadequate nutrition resulting from poor diet, malabsorption, or abnormal nutrient distribution. "Plasma levels of Syn1 and HA significantly decreased after 60 days post discharge among children with either initial phenotype who fully recovered from malnutrition without further acute illness following discharge." (PMID 35398787, 2022).
medulloblastoma (1 paper, 2020). A malignant, invasive embryonal neoplasm arising from the cerebellum. "The results showed lower expression of SYN1 and SNAP25 in the medulloblastoma subtypes compared to normal cerebellum." (PMID 32720471, 2020).
mood disorder (1 paper, 2016). A cognitive disorder a disturbance in which the person's mood is hypothesized to be the main underlying feature. "Synapsin genes – Synapsin I (SYN1), Synapsin II (SYN2), and Synapsin III (SYN3) – are interesting candidates for the etiology of mood disorders due to their involvement in the adult brain in synaptic transmission and plasticity, as well as in brain development in axon outgrowth and synaptogenesis." (PMID 27515700, 2016).
muscular dystrophy (1 paper, 2016). Muscular dystrophy (MD) refers to a group of more than 30 genetic diseases characterized by progressive weakness and degeneration of the skeletal muscles that control movement. "Altogether the newly identified regulatory pathway miR-143/β-dystrobrevin/synapsin I provides novel insights into the functions of β-dystrobrevin and opens up new perspectives for elucidating the molecular mechanisms underlying the neuronal involvement in muscular dystrophy." (PMID 27223470, 2016).
myocardial infarction (1 paper, 2021). Gross necrosis of the myocardium, as a result of interruption of the blood supply to the area, as in coronary thrombosis. "We estimated the staining consistency of the metabolic radiotracer [18F]-FDG with the perfusion radiotracer (SYN1) with impaired cardiac function due to myocardial infarction when confronted with MRI heart performance indicators." (PMID 34830471, 2021). "The precise division of the mouse heart showed the validity of the use of SYN1 in the imaging of myocardial infarction." (PMID 34830471, 2021). "In our study, the mice myocardial infarction model (LAD ligation) was used to compare SYN1 to other two gold standard imaging systems—[18F]-FDG PET/CT and MRI (magnetic resonance imaging/CMR—cardiac magnetic resonance)." (PMID 34830471, 2021). "Considering the remodelling of the heart and its enlargement after myocardial infarction, it can also be observed that the SYN1 radiotracer showed similar areas in terms of volume in normal and postinfarction mice compared to the [18F]-FDG metabolic radiotracer." (PMID 34830471, 2021).
neuropathic pain (1 paper, 2019). Chronic pain caused by damage to nerve fibers. "In this study, we found that acupuncture treatment recovered the decreased levels of phosphorylated Syn-1 and PSD-95 in the hippocampus of PSNL-induced neuropathic pain." (PMID 31616240, 2019).
preeclampsia (1 paper, 2019). Preeclampsia is a hypertensive disorder of pregnancy that is characterized by new-onset hypertension with proteinuria presenting after 20 weeks of gestation, and depending on mild or severe forms may initially present with severe headache, visual disturbances, and hyperreflexia. "Preeclampsia is characterized by shallow placentation and resultant hypoxia-reoxygenation damage and several authors have assessed the protein and RNA dynamics of SYN1 and its receptor in in vitro and ex vivo models of placental hypoxia." (PMID 31862915, 2019).
RSV bronchiolitis (1 paper, 2023). "Present results highlight, for the first time, that in children hospitalized for acute RSV bronchiolitis, the transcriptional levels of pol genes of HERV-H, -K, and -W, as well as of env genes of SYN1 and SYN2 were significantly lower than in HC." (PMID 36826024, 2023). "The medians of the transcription levels of HERV-H-pol, HERV-K-pol, and HERV-W-pol, as well as of SYN1-env and SYN2-env, were significantly lower in children with RSV bronchiolitis as compared to HC." (PMID 36826024, 2023).